IGFBP1 (insulin like growth factor binding protein 1)
Diseases named in the same sentence as IGFBP1 in open-access papers (continued):
Sharing a sentence is not in itself a finding about the gene and the disease.
Stroke (10 papers, 2010 to 2025). Sudden impairment of blood flow to a part of the brain due to occlusion or rupture of an artery to the brain. "The results of two genetic studies have suggested that a single-nucleotide polymorphism (rs1874479) in the IGFBP1 gene is associated with increased stroke risk." (PMID 37298072, 2023). "Within carotid arteries, IGFBP-1 has been demonstrated to be associated with intima–media thickness, which may predispose patients with carotid stenosis and stroke." (PMID 40710778, 2025). "Additionally, several proteins that drove diseases such as RER1 enhancing carcinogenesis and stemness of pancreatic cancer and Igfbp1 confirmed as stroke risk marker were also increased in liver after caffeine administration." (PMID 38188177, 2024). "The temporal profile of s-IGFBP-1, i.e., whether the sample was taken acutely or after 3 months, seemed to alter the subtype of stroke in which s-IGFBP-1 was associated with long-term mortality." (PMID 37298072, 2023). "Additionally, higher s-IGFBP-1 was associated with increased risk of mortality in some subtypes of stroke." (PMID 37298072, 2023). "In summary, our results suggest that s-IGFBP-1 after 3 months, which possibly resembles s-IGFBP-1 under poststroke steady-state conditions, is an independent predictor of the long-term outcome after stroke regarding functional independence and all-cause mortality." (PMID 37298072, 2023). "Therefore, we used the Sahlgrenska Academy Study on Ischemic Stroke (SAHLSIS) cohort to investigate whether s-IGFBP-1 levels in the acute phase or 3 months after stroke are associated with outcome after stroke in terms of functional independence and mortality." (PMID 37298072, 2023). "Compared with the more robust associations between 3-month s-IGFBP-1 and long-term poststroke outcomes, this suggests that s-IGFBP-1 measured in the latter stages of stroke recovery is of more value as a prognostic marker of poststroke outcome." (PMID 37298072, 2023). "We found different levels of s-IGFBP-1 in the stroke subtypes after 3 months, as s-IGFBP-1 was increased in small vessel occlusion and cardioembolic stroke." (PMID 37298072, 2023). "rs1874479 at IGFBP1 was significantly associated with CCVD, particularly with stroke, and the HRs of the additive model were 1.310 (P=0.007) and 1.372 (P=0.015)." (PMID 29100429, 2017). "The G allele of rs1874479 at IGFBP1 was associated with an increased risk of incident stroke and CCVD, particularly stroke." (PMID 29100429, 2017). "Larger studies with more events are needed to determine whether IGFBP-1 can predict MI, stroke, and death individually." (PMID 40710778, 2025). "In another subcohort of the Cardiovascular Health Study (n = 2268), a higher two-hour s-IGFBP-1 post-oral glucose tolerance test, but not fasting s-IGFBP-1, was associated with increased risk of major health events (which included stroke) and mortality." (PMID 37298072, 2023). "Although longitudinal measurements of s-IGFBP-1 have previously not been performed in stroke patients, this finding is in some accordance with the earlier observation of unchanged baseline fasting plasma IGFBP-1 in older adults that later developed stroke compared with controls." (PMID 37298072, 2023). "This study investigated the association between s-IGFBP-1 levels and poststroke outcome in a stroke population, which has not been performed previously." (PMID 37298072, 2023). "In terms of mortality, we observed an association between 3-month s-IGFBP-1 and all-cause mortality, i.e., all mortality including not only mortality due to stroke or other cardiovascular mortality." (PMID 37298072, 2023). "In the present study, s-IGFBP-1 in the acute phase of stroke was similar to that in the controls." (PMID 37298072, 2023). "rs1874479 in IGFBP1 was associated with a risk of incident CCVD, particularly stroke." (PMID 29100429, 2017).
Stroke (continued). "Thus, in line with our results, the data from other cohorts not suffering from stroke indicate that high s-IGFBP-1 is associated with an increased risk of all-cause mortality and not only cardiovascular mortality." (PMID 37298072, 2023). "We hypothesized that high s-IGFBP-1 would predict worse stroke outcome as previously seen after MI." (PMID 37298072, 2023). "In summary, little is known whether s-IGFBP-1 can predict the outcome after stroke." (PMID 37298072, 2023). "However, overall, acute s-IGFBP-1 was a weaker predictor of functional outcome following stroke." (PMID 37298072, 2023). "Therefore, the predictive value of s-IGFBP-1 may be higher in some stroke subtypes, but this remains to be elucidated in further studies." (PMID 37298072, 2023). "In addition to these, certain other IGF binding proteins are evidently influenced by hormone therapy and may be related to CHD (IGFBP1) or stroke (IGFBP2, IGFBP6)." (PMID 20667078, 2010). "Insulin-like growth factor-binding protein-1 (IGFBP-1) regulates insulin-like growth factor-I (IGF-I) bioactivity, and is a central player in normal growth, metabolism, and stroke recovery." (PMID 37298072, 2023). "The present study found that s-IGFBP-1 levels were higher in stroke patients after 3 months, but not in the acute phase after stroke, compared with controls." (PMID 37298072, 2023). "In line with this, our patients had a non-significant tendency of lower s-IGFBP-1 values acutely after stroke, albeit after 3 months, s-IGFBP-1 was prominently higher than in the controls." (PMID 37298072, 2023). "However, to our knowledge, the relationship between s-IGFBP-1 and poststroke functional outcome and survival has previously not been examined in a stroke population." (PMID 37298072, 2023). "Furthermore, in a subcohort of the Cardiovascular Health Study (n = 2026), baseline fasting plasma IGFBP-1 was similar in adults aged 65 years or older that later developed stroke compared with control subjects, and IGFBP-1 did not predict the risk of stroke." (PMID 37298072, 2023). "Moreover, we analyzed whether there was a correlation between the day after stroke onset when the blood sample was collected and the median level of s-IGFBP-1, and there was no such correlation in the acute phase." (PMID 37298072, 2023). "However, high acute s-IGFBP-1 was significantly related to poor functional outcome 7 years poststroke, even when patients who died were excluded, which may implicate that s-IGFBP-1 was of a lower significance in the acute to early subacute phase of stroke." (PMID 37298072, 2023).
type 1 diabetes (10 papers, 2014 to 2025). "Previous studies of individuals affected by type 1 diabetes and AAb+ individuals have revealed increased serum IGFBP1 levels." (PMID 37537394, 2023). "In type 1 diabetes with insulinopenia, the IGFBP-1 levels are high because of low levels of portal insulin." (PMID 35586622, 2022). "It has been reported that insulin withdrawal for 8 h in patients with type 1 diabetes treated with CSII increased IGFBP1 concentrations sixfold, and it is conceivable that the high IGFBP1 values could be due to a lag in insulin delivery." (PMID 24327601, 2014). "Type 1 diabetes (T1D) and DN had increased circulating IGFBP-1 level and decreased DNA methylation levels of the IGFBP-1 gene." (PMID 35002740, 2021). "People with DN have a significant increase in their plasma IGFBP-1 and IGFBP-4, more importantly, IGFBP-4 fragments (including N- and C-terminal fragments (NT-IGFBP-4 and CT-IGFBP-4)) are related to cardiovascular mortality in type 1 diabetes patients no matter with or without nephropathy." (PMID 35002740, 2021).
atherosclerosis (9 papers, 2017 to 2025). A disease characterized by the build-up of fatty material and calcium deposition in the arterial wall resulting in partial or complete occlusion of the arterial lumen. "The relationship between IGFBP-1 and MACE is complex, given studies suggesting that lower levels are associated with poor metabolic profiles and IGFBP-1 overexpression can be protective against atherosclerosis." (PMID 40710778, 2025). "This review explores these associations and the possible roles of IGFBP-1 in the pathophysiology of atherosclerosis." (PMID 39595651, 2024). "Cross-sectional data also support an association between low IGFBP-1 levels, cardiovascular risk, and subclinical atherosclerosis." (PMID 32190801, 2020). "The association between circulating IGFBP-1 concentrations and cardiovascular disease risk and outcomes will then be reviewed, followed by an exploration of possible roles in the pathophysiology of atherosclerosis." (PMID 39595651, 2024). "Lewitt and colleagues (2024) reviewed the role of IGFBP-1 in cardiovascular disease, emphasizing its involvement in cellular growth, signaling, and metabolic regulation—pathways central to angiogenesis, atherosclerosis, and thrombosis." (PMID 40710778, 2025). "Our study builds on these findings by showing that IGFBP-1 is associated with increased 2-year MACE risk in patients with PAD, highlighting its potential role in the progression of atherosclerosis in multiple arterial beds." (PMID 40710778, 2025). "We have previously reported that human IGFBP-1, when overexpressed in mice, leads to vascular insulin sensitization; increased nitric bioavailability; reduced atherosclerosis; and enhanced vascular repair." (PMID 32190801, 2020). "Our study revealed that IGFBP-1 is a circulating growth factor independently associated with the occurrence of MACE over two years of follow-up among patients with PAD, highlighting its potential role as a biomarker for systemic atherosclerosis progression." (PMID 40710778, 2025). "In ApoE-/- mice, overexpression of IGFBP1 reduced atherosclerosis." (PMID 38157252, 2023). "In both obese and non-obese mouse models, IGFBP-1 overexpression was associated with reduced blood pressure, improved insulin sensitivity, enhanced vasodilation, increased endothelial nitric oxide production, and protection against atherosclerosis." (PMID 40710778, 2025). "We speculate that IGFBP-1 may have different endocrine and paracrine roles in atherosclerosis." (PMID 39595651, 2024). "In isolated segments of mouse aorta from wild-type and IGF1R knockout mice, overexpression of human IGFBP-1 increases endothelial nitric oxide production independently of IGF-I and protects against atherosclerosis." (PMID 39595651, 2024). "The third LoF SNP ‘rs117054298’ belongs to insulin-like growth factor (IGF) binding protein-1 (IGFBP1), whose splice site of one transcript ENST00000457280 is disrupted and contributes to atherosclerosis." (PMID 29420653, 2018). "However, it should be recognized that both IGFBP-1 and IGF-I stimulate nitric oxide generation and have been shown to reduce atherosclerosis in mice." (PMID 32190801, 2020). "Notably, these correlations might suggest a link between the metabolome and protein markers related to immune signalling (LTα, CD6, CCL21, SELE), energy balance and metabolism-related hormones (IGFBP1, SHGB, ADM, leptin, and STC1), and atherosclerosis/thrombosis inhibitor (PAI1)." (PMID 39154540, 2024). "Insulin-sensitizing, blood pressure-lowering, and antiatherosclerotic properties of IGFBP-1 have been demonstrated, raising the possibility that increasing IGFBP-1 levels may be a therapeutic option to protect individuals from IR, arterial hypertension, and atherosclerosis." (PMID 32911852, 2020).
diabetic nephropathy (9 papers, 2012 to 2023). "In this study, we examined levels of circulating ANGPTL4 in people with diabetic nephropathy (DN) and its association with established DN-associated proteins such as IGFBP1 and IGFBP4." (PMID 31772941, 2019). "In the present study, we evaluated the epigenetic changes of IGFBP1 in T1D and diabetic nephropathy (DN)." (PMID 24904693, 2014). "Another recent study has shown that T1D patients have decreased DNA methylation in the insulin-like growth factor binding protein-1 (IGFBP-1) that correlates with increased circulating IGFBP-1 levels and the presence of diabetic nephropathy." (PMID 25566322, 2014). "The rise in IGFBP1 was reported previously in an animal model of the diabetic kidney disease." (PMID 31772941, 2019). "The strongly upregulated genes IGFBP1 and IGFBP3 have been suggested as markers for diabetic nephropathy and chronic kidney disease." (PMID 32197499, 2020). "Collectively, our data showed people with DN to have elevated levels of IGFBP1 and IGFBP4, which comes in agreement with previous reports and suggests the elevation of these IGFBPs as indicative factors of a diabetic kidney disease." (PMID 31772941, 2019). "Furthermore, we analyzed insulin-like growth factor 1 (IGF-1) and IGF-binding protein 1 (IGFBP-1) since the IGFBP-1 and IGF1 have been shown to be associated with diabetes nephropathy independent of the degree of albumin." (PMID 22400116, 2012).
heart failure (9 papers, 2018 to 2025). Inability of the heart to pump blood at an adequate rate to meet tissue metabolic requirements. "In contrast, in studies examining the prognostic value of IGFBP-1 for long-term outcome after MI, high s-IGFBP-1 at admission was associated with future hospitalization for heart failure, long-term mortality, and both cardiovascular morbidity and long-term mortality." (PMID 37298072, 2023). "In patients with a first acute MI, elevated IGFBP-1 levels predicted subsequent heart failure development." (PMID 40710778, 2025). "In that study, IGFBP-1 increased while IGF-I further decreased in the heart failure group over a mean 53-month follow-up period." (PMID 39595651, 2024). "In a study of proteomics in heart failure (n = 1134, mean 70 y, 32% F), IGFBP-1 demonstrated the largest treatment effect, with a fall of more than 70% in response to the sodium–glucose cotransporter 2 inhibitor empagliflozin." (PMID 39595651, 2024). "One study in a community setting has shown that, while IGFBP-1 alone predicted incident heart failure and cardiovascular disease mortality, IGFBP-2 and IGF-I were more useful in a multimarker model." (PMID 39595651, 2024). "In a study of survivors of a first acute myocardial infarction (n = 853, mean 60 y, 34% F), higher IGFBP-1 predicted heart failure as well as mortality over an eight-year follow-up." (PMID 39595651, 2024). "In that study, higher IGFBP-1 also predicted heart failure in the control group (n = 1106, mean 61 y, 36% F)." (PMID 39595651, 2024). "In humans, increased levels of IGFBP-1 not only predicted heart failure in a prospective study after myocardial infarction but also overall mortality over 8 years." (PMID 33686453, 2021). "Several biomarkers—including IGFBP-1, IGFBP-2, IGFBP-3, FGF-23, MMP-2, MMP-7, TIMP-2, and RAGE/AGE—were significantly elevated in patients with cardiac involvement and independently associated with either heart failure decompensation or death/transplantation." (PMID 41226753, 2025). "IGFBP-1 is seen as a marker of myocardial damage and related to heart failure." (PMID 39711764, 2024). "Higher IGFBP-1 has been identified as a long-term predictor of heart failure (HF)." (PMID 39595651, 2024). "Likewise, in survivors of a previous (first) AMI, higher circulating IGFBP-1 concentrations predicted heart failure as demonstrated by a prospective study which included male and female subjects between 45 and 70 years of age." (PMID 30061864, 2018). "In diabetic patients, IGFBP-1 concentrations were associated with those of copeptin, which independently predicted myocardial events, and this could in part explain the prognostic value of IGFBP-1 for heart failure or AMI." (PMID 30061864, 2018). "IGFBP-1 and IGFBP-2 have previously been shown to predict mortality in heart failure and are elevated in other fibrotic diseases, such as idiopathic pulmonary fibrosis." (PMID 41226753, 2025). "Interestingly, higher IGFBP-1 concentrations were informative for mortality in subjects with no history of heart failure after a follow-up of 8 years." (PMID 30061864, 2018). "Moreover, it was shown that the concentration of IGF-binding protein (IGFBP)-1 and the ratio of IGFBP-1/IGF-1 in patients with heart failure were significantly lower than in a control group, and they can be used to easily identify patients with and without heart failure." (PMID 37372424, 2023).
pancreatic cancer (9 papers, 2008 to 2024). "However, in another study, it was concluded that low circulating IGFBP1 levels significantly predicted a high risk of pancreatic cancer." (PMID 32414222, 2020). "In addition to pancreatic cancer, IGFBP1 has been reported to be closely associated with metastasis in several other common digestive system tumours." (PMID 33164330, 2020). "Thakur et al20 have reported that liver metastases of pancreatic cancer show high expression of IGFBP1 compared with the primary tumour." (PMID 33164330, 2020). "Gene expression analyses in the primary pancreatic tumor, as well as metastatic liver lesions, have identified IGFBP1, SERPINA1, and WT1 as clinically useful biomarkers for prognostic and therapeutic purposes in metastatic pancreatic cancer." (PMID 32414222, 2020). "Intriguingly, we observed highly upregulated expression of Igfbp1 and Serpina1 in liver metastatic tissues compared to primary pancreatic tumors and normal pancreas." (PMID 18218118, 2008). "We verified two genes in human cell lines, Igfbp1 and Serpina1a, these genes were highly upregulated in liver metastaic tissues compared to primary pancreatic tumors from transgenic mice." (PMID 18218118, 2008). "We identified Igfbp1, Serpina1 and Wt1 genes that are likely to be clinically useful biomarkers for prognostic or therapeutic purposes in metastatic pancreatic cancer, particularly in pancreatic cancer where c-Myc is overexpressed." (PMID 18218118, 2008). "Observed significant association between pancreatic cancer risk and polymorphisms in IGF1, IGF1R & IGFBP1 but SNPs in IGFBP5 were not significant." (PMID 36465383, 2022). "Verification of Igfbp1 and Serpina1 by RT-PCR and quantitative PCR showed strong expression in liver metastatic lesions but there was a lack of expression of these genes in primary pancreatic tumors or normal pancreas." (PMID 18218118, 2008).
gestational diabetes (8 papers, 2016 to 2024). Carbohydrate intolerance first diagnosed during pregnancy. "One study reported an inverse association between IGFI or IGFBP1 and risk for gestational diabetes; another reported a positive association between IGFI or IGFBP3 and risk for gestational diabetes." (PMID 27833901, 2016). "Based on the study of IGFBP1-7 in obese pregnant women, women with gestational diabetes, and their fetuses, Lappas found that preexisting maternal obesity and gestational diabetes are associated with lower levels of IGFBP-1 and IGFBP-7 in maternal and cord plasma." (PMID 35813634, 2022). "Other data show that prior to routine screening for gestational diabetes mellitus (GDM), exposure of the fetus to altered amniotic fluid glucose, insulin, and insulin-like growth factor-binding protein 1 has occurred." (PMID 37176607, 2023). "Further studies will be needed to assess the role of IGFBP-1, phIGFBP-1 and MMP-8 in maternal metabolism throughout the entire course of pregnancy, both in normal weight women and in relation to clinical manifestations like gestational diabetes." (PMID 32923723, 2020). "Furthermore, reduced IGFBP-1 levels have been detected in women with gestational diabetes when compared to those without this disease." (PMID 32923723, 2020).